DCC (DCC netrin 1 receptor)
Diseases named in the same sentence as DCC in open-access papers (continued):
Sharing a sentence is not in itself a finding about the gene and the disease.
neuroblastoma (7 papers, 2010 to 2023). Neuroblastoma (NB) is the most common solid, extracranial childhood tumor. "On SH-SY5Y neuroblastoma cells, chymotrypsin produced a similarly selective loss of DCC expression at concentrations similar to those active in intact adult tissue, with approximately 50 % loss of DCC at 300nM." (PMID 27716118, 2016). "DeGeer and colleagues reported that tyrosine phosphorylation of Trio regulates netrin-1/DCC-mediated cortical axon outgrowth in N1E–115 neuroblastoma cells." (PMID 37528624, 2023). "We and others have previously reported that γ-secretase-dependent accumulation of Deleted Colorectal Cancer C-terminal fragment (DCC-CTF) promotes neurite outgrowth in neuroblastoma cells and motor neuron explants." (PMID 27196744, 2016). "DCC CTF undergoes intramembraneous proteolysis by γ-secretase, and accumulation of DCC CTF in neuroblastoma cells treated with γ-secretase inhibitors stimulates neurite outgrowth." (PMID 20798900, 2010). "Since the levels of DCC are low in cancer-derived cell lines, netrin-4 was used in these experiments, since this is an effective ligand for neogenin, which is abundant in SH-SY5Y neuroblastoma cells." (PMID 27716118, 2016).
ovarian carcinoma (7 papers, 1995 to 2020). A malignant neoplasm originating from the surface ovarian epithelium. "Loss of expression of the DCC gene product detected by immunohistochemistry significantly correlated with the loss of mRNA expression in ovarian carcinomas (P = 0.01 by chi-square test) or in both endometrial and ovarian carcinomas combined (P = 0.001)." (PMID 7880725, 1995). "The expression of DCC is mostly lost or reduced in later clinical stage, higher pathological grade, and poor prognosis in ovarian cancer." (PMID 27127179, 2016). "Among the most interesting cases are the rare germline CNVs affecting RET in GBMs, ERBB2 in renal cell carcinomas, and DCC in ovarian cancers." (PMID 25644941, 2015). "Our purpose was to investigate whether NTN1 and its receptor DCC may be involved in ovarian cancer." (PMID 21789787, 2011). "Previous report indicated 52% of malignant ovarian cancers did not express the DCC gene, and also suggested a significant correlation exists between DCC expression and ovarian cancer." (PMID 24565108, 2013).
glioma (6 papers, 2011 to 2024). A benign or malignant brain and spinal cord tumor that arises from glial cells (astrocytes, oligodendrocytes, ependymal cells). "A loss of expression of DCC (Deleted in Colorectal Carcinoma), the receptor for netrin has been found to correlate with glioma progression." (PMID 23050142, 2012). "Gain of netrin-1 and/or loss of DCC would accelerate glioma progression." (PMID 22666451, 2012). "As expected, the phenotype for loss of neogenin expression could be similar to DCC, inactivation of which helped to further glioma progression and glioblastoma regeneration." (PMID 22666451, 2012). "Perhaps other mechanisms like loss of heterozygosity or gene mutations which have been reported in DCC and Unc5H could further provide more evidence to elaborate neogenin’s role in gliomas." (PMID 22666451, 2012). "Importantly, endogenous DCC has previously been demonstrated to render several glioma cell lines migratory in response to a gradient of NTN1 as a chemoattractant." (PMID 33871356, 2021). "This suggests that DCC signalling does not mediate programmed cell death but rather promotes remodelling of the actin cytoskeleton in glioma and neuroblast cells in a similar manner to neurons and oligodendrocytes." (PMID 33871356, 2021). "Although DCC was highly expressed in normal mouse brains, none of the three glioma cell lines expressed DCC." (PMID 28710382, 2017).
lung carcinoma (6 papers, 2013 to 2025). "To further compare and contrast the effects of sotorasib and DCC-3116, either alone or in combination in GEM models of lung cancer and because of noted correlations between loss of LKB1 and insensitivity of cancers to various types of therapy, we employed our KP mouse model." (PMID 39213022, 2024). "First preclinical studies revealed that the inhibition of netrin-1 interaction with its receptors by a decoy recombinant DCC fragment (DCC-5Fbn) led to increased tumor cell death and significant reduction of the tumor mass in a murine xenograft lung cancer model." (PMID 24647424, 2014). "Moreover, the combination of DCC-3116, a selective ULK1/2 inhibitor, plus sotorasib displays cooperative/synergistic suppression of human KRASG12C-driven lung cancer cell proliferation in vitro and superior tumor control in vivo." (PMID 39213022, 2024).
colorectal tumors (5 papers, 1994 to 2024). "Tumor suppressor genes are localized within this region, including the gene Deleted in Colorectal Carcinoma (DCC), mutations of which are rarely detected in human colorectal tumors (6%)." (PMID 29283387, 2017). "Along this line, it was recently reported that conditional inactivation of DCC expression or invalidation of DCC‐induced apoptosis by introduction of a D1290N point mutation is, respectively associated with breast and colorectal tumor progression in two mutant mice models." (PMID 26882243, 2016).
endometrial cancer (4 papers, 1995 to 2025). Primary or metastatic malignant neoplasm involving the endometrium (mucous membrane that lines the endometrial cavity). "Loss of heterozygosity of the DCC gene was detected in one of seven (14%) informative cases of endometrial carcinomas, 1 of 11 (9%) informative cases of cervical carcinomas and two of six (33%) informative cases of ovarian tumours." (PMID 7880725, 1995).
glioblastoma (4 papers, 2011 to 2024). The most malignant astrocytic tumor (WHO grade IV). "Using human glioblastoma cell lines, we provide evidence that DCC is required for chemoattraction to netrin-1 and slows the rate of spontaneous cell migration." (PMID 21980448, 2011). "We determined that the human glioblastoma cell lines U87, U343, and U373 all express neogenin, UNC5 homologues, and netrin-1 or netrin-3, but only U87 cells express DCC." (PMID 21980448, 2011).
Cerebral ischemia (3 papers, 2017 to 2021). Restriction of arterial blood supply to the brain associated with insufficient oxygenation to support the metabolic requirements of the tissue. "Our previous study found that treadmill exercise significantly increased the expression of Netrin-1 and its receptor DCC after the acute stage of cerebral ischemia injury." (PMID 29487502, 2018). "So, we hypothesize that Netrin-1 binding to DCC may participate in the complicated process of neural regeneration after a cerebral ischemia." (PMID 29487502, 2018). "Alternatively, a study on cerebral ischemia demonstrated that after stroke, NTN4 is upregulated in astrocytes and blood vessels of the ischemic core, and DCC but not UNC5B is upregulated in neuronal processes." (PMID 33923095, 2021).
diffuse large B-cell lymphoma (3 papers, 2016 to 2024). "In human diffuse large B‐cell lymphoma (DLBCL) and mantle cell lymphoma (MCL) biopsies tissues, upregulation of the NTN1/DCC expression ratio tipped the scales towards loss of DCC‐induced apoptosis." (PMID 38546656, 2024). "In human diffuse large B‐cell lymphoma (DLBCL), an imbalance of the netrin‐1/DCC ratio suggests a loss of DCC‐induced apoptosis, either via a decrease in DCC expression in germinal center subtype or by up‐regulation of netrin‐1 in activated B‐cell (ABC) one." (PMID 26882243, 2016). "Here, we report that, in addition to intestinal malignancies, DCC‐D1290N mutant mice are prone to develop B‐cell type lymphoid hyperplasia and follicular (FL) to diffuse large B‐cell lymphoma (DLBCL) with age." (PMID 26882243, 2016). "In human diffuse large B cell lymphoma (DLBCL), they demonstrate an imbalance of the netrin-1/DCC ratio which suggests a loss of DCC-induced apoptosis, either via a decrease in DCC expression in the GC subtype or by upregulation of netrin-1 in activated B cell (ABC) one." (PMID 27398102, 2016).
gallbladder cancer (3 papers, 2016 to 2021). "DCC rs714 A > G polymorphism, the most widely studied SNP of DCC gene, is LOH marker associated with decreased expression of DCC and with increased risk of colorectal and gallbladder cancer." (PMID 26891331, 2016).
mantle cell lymphoma (3 papers, 2016 to 2024). Mantle cell lymphoma is a rare form of malignant non-Hodgkin lymphoma affecting B lymphocytes in the lymph nodes in a region called the ``mantle zone''. "In human, loss of DCC‐induced apoptosis is retrieved in 2 types of B‐cell lymphoma, diffuse large B‐cell lymphoma (DLBCL) and mantle cell lymphoma (MCL), either via a decrease in DCC expression or by up‐regulation of netrin‐1." (PMID 26882243, 2016). "In human lymphoma, DCC mRNA expression was decreased in GC-DLBCL compared with control tonsils and in mantle cell lymphomas." (PMID 36136711, 2022).
meningioma (3 papers, 2016 to 2019). A generally slow growing tumor attached to the dura mater. "In conclusion, based on its expression levels, DCC may constitute a valid biomarker to identify those benign meningiomas at risk for progression." (PMID 27096627, 2016). "We performed a meta-analysis using publicly accessible array studies to investigate CSC expression profiles in meningiomas grouped according to their DCC netrin 1 receptor (DCC) expression levels or by tumor grade." (PMID 31083655, 2019). "In meningiomas, an array expression study has identified DCC as a candidate gene for early meningioma progression." (PMID 31083655, 2019). "The type I transmembrane protein podocalyxin like (PODXL) was markedly upregulated in DCC low expression meningiomas in six studies." (PMID 31083655, 2019). "In our survey, PROM1 was markedly downregulated in DCC low expression meningiomas in five array expression studies." (PMID 31083655, 2019). "BMP/retinoic acid inducible neural specific 1 (BRINP1), and PROM1 were significantly downregulated in DCC low expression meningiomas in five studies." (PMID 31083655, 2019). "This can be partially attributed to the fact that a subset of benign meningiomas bear the capacity to evolve into more aggressive meningiomas and DCC expression levels are an appropriate molecular discriminator reflecting this characteristics." (PMID 31083655, 2019). "The resulting gene expression levels enabled us to categorize the meningiomas either as DCC low, DCC medium, or DCC high expression tumors." (PMID 27096627, 2016). "We noticed DCC as a DEG when we applied ANOVA to compare each of the 14 meningiomas with the group of three BN samples to assess variation in expression levels among the tumors and between tumors and BN samples." (PMID 27096627, 2016). "An RT-PCR analysis on the five DCC high expression and six DCC low expression meningiomas substantially supported the microarray expression data." (PMID 27096627, 2016). "The DCC netrin 1 receptor (DCC) is a candidate gene for early meningioma progression." (PMID 31083655, 2019). "DCC has not been so far identified in other microarray expression studies as a gene specifically associated with meningioma progression." (PMID 27096627, 2016). "In summary, this microarray expression study identified DCC as a candidate gene for early meningioma progression which could provide an explanation for the observed discrepancies between histopathological and molecular classification of meningiomas." (PMID 27096627, 2016). "By utilizing whole transcript oligonucleotide arrays, we identified DCC as a candidate gene for tumor progression in grade I and II meningiomas using an initial multiple group comparison that was performed on each meningioma against the BN samples which served as control set." (PMID 27096627, 2016). "As meningiomas are slow growing tumors, cell culture experiments on clinical meningioma samples with WHO grade I but DCC low expression profile could probably rule out the capacity of these tumors to progress into more aggressive cancer cells." (PMID 27096627, 2016). "However, no significant role for DCC alterations has been found in the pathogenesis of meningiomas." (PMID 27127179, 2016).
myeloma (3 papers, 2017 to 2026). "Moreover, after coprecipitation of H3K36me3-associated RNAs by RIP, DCC mRNA was less enriched than STAiR2, indicating that the expression of DCC wild type plays a minor role in INA-6 myeloma cells compared to both, STAiR2 and the hybrid." (PMID 28801664, 2017). "Hence, the IL-6-induced alternative splicing of the DCC locus probably leads to an impaired protein function and may contribute to myeloma cell survival." (PMID 28801664, 2017). "Therefore, we aimed at elucidating whether STAiR2 has an impact on DCC expression in multiple myeloma cells." (PMID 28801664, 2017).
Obesity (3 papers, 2022 to 2025). Accumulation of substantial excess body fat. "Subsequently, we compared the impact of the adipocyte-derived secretome from patients with obesity and NTN-1 on the expression levels of NEO1, DCC, and UNC5B in two human colorectal cell lines, Caco-2 and HT-29." (PMID 36831381, 2023).
pancreatic cancer (3 papers, 2011 to 2023). "Mutations and loss of DCC have previously been implicated in pancreatic cancer, as well as a range of other tumour types." (PMID 21750719, 2011). "In turn, the most commonly deleted gene was MYOCD, a cancer related gene which also displayed LOH in most of our cases (80%); other frequently deleted cancer-associated genes included the EYA3, NR2C1, PTAFR, and the DCC cancer associated genes which have also been involved in pancreatic cancer." (PMID 21811587, 2011).
colorectal adenocarcinoma (2 papers, 2023). The most common type of colorectal carcinoma. "Chromosome 18q is the location of the DCC, DPC4 (SMAD4; MADH4), and JV-18 (SMAD2; MADH2) genes, and loss is frequent in colorectal adenocarcinoma." (PMID 37509254, 2023). "Furthermore, both NTN-1 and ACM were found to increase NEO1 and DCC mRNA levels in two colorectal adenocarcinoma cell lines, together with UNC5B downregulation in HT-29 cells when stimulated with ACM." (PMID 36831381, 2023).
dysplasia (2 papers, 2008 to 2009). A usually neoplastic transformation of the cell, associated with altered architectural tissue patterns.
esophageal carcinoma (2 papers, 2023 to 2025). A primary or metastatic malignant neoplasm involving the esophagus. "Looking for esophageal carcinoma susceptibility in OMIM, we found listed at #133239 RNF6 and DCC; the latter, according to the STRING database, is linked by experiments/co-expression/co-occurrence to TRIO (5p15.2)(a) and MYO10 (5p15.1)(p)." (PMID 38248360, 2023).
Intellectual disability (2 papers, 2023 to 2024). "The present patient harboured a novel monoallelic DCC missense variant associated with delayed psychomotor development, intellectual disability, MMs and complete ACC." (PMID 38398422, 2024). "Biallelic loss-of-function DCC variants have also been reported in patients with developmental split-brain syndrome (DSBS, MIM# 617542), a more complex syndrome associated with ACC, intellectual disability, scoliosis and horizontal gaze palsy, with or without mirror movements (MMs)." (PMID 38398422, 2024).
intestinal tumor (2 papers, 2011 to 2022). "Contrary to the effect of Netrin-1, DCC acts as an inhibitor of cell invasion, tumor growth and metastasis 75, and limits the progression of intestinal tumors in mouse models." (PMID 36147476, 2022).
ischemic stroke (2 papers, 2017 to 2021). A stroke disorder caused by obstruction of blood flow to the brain, due to thrombotic (local blood clot formation) or embolic (due to a blood clot or other material traveling from another site) event. "In conclusion, our studies suggested that engrafted OPCs promoted the recovery after ischemic stroke by enhancing endogenous oligodendrogenesis, neurite growth, and synaptogenesis; the last two being mediated by the Netrin-1/DCC axis." (PMID 34881088, 2021). "Taken together, we hypothesize that netrin-1 and its receptor DCC may also be involved in the beneficial effects of ADSC transplantation on the neurological recovery after ischemic stroke in rats." (PMID 29017609, 2017). "To determine whether netrin-1 and DCC are involved in the neural protection induced by ADSC transplantation after ischemic stroke, we measured their temporal and spatial expression patterns in the brains of MCAO rats." (PMID 29017609, 2017).
lymph node metastases (2 papers, 2010 to 2016). "According to our study, the DCC rs2229080 polymorphism was associated with the lymph node metastasis status." (PMID 27127179, 2016).
lymphoma (2 papers, 2016 to 2022). A malignant (clonal) proliferation of B- lymphocytes or T- lymphocytes which involves the lymph nodes, bone marrow and/or extranodal sites. "DCC was shown to be lost in several cancers among which lymphoma some years ago, but its suppressive function in these cancers is not established." (PMID 26882243, 2016). "We report here that inhibition of DCC‐induced apoptosis is sufficient to increase lymphoma occurrence in a transgenic mice model." (PMID 26882243, 2016).
mental disorder (2 papers, 2020 to 2022). A disease that has its basis in the disruption of mental process. "Our study identified multiple risk behaviors associated genes, which have been suggested to be involved in the development of mental disorders, such as APBB2 and DCC." (PMID 32090979, 2020). "The list of pleiotropic risk factors acting across a variety of psychiatric disorders includes such well-described candidates as NEGR1, SOX5, SORCS3, DCC, and TCF4 and indicates that MDD and PTSD are part of the greater spectrum of mental disorders with shared genetic liability." (PMID 33905376, 2022).
oral squamous cell carcinoma (2 papers, 1999 to 2024).
ovarian tumors (2 papers, 1995 to 2011). "In contrast, DCC was found downregulated in 59% (10/17) of ovarian tumors tested but correlation was not significant when compared to normal or benign specimens." (PMID 21789787, 2011).
skin cutaneous melanoma (2 papers, 2015 to 2025). "Surprisingly, four of the genes containing RRA missense mutaions in Uveal Melanoma (DCC, CR1, GCC2 and CLCN1) were predicted as diver genes in TCGA skin cutaneous melanoma dataset." (PMID 25903059, 2015).
Stroke (2 papers, 2017 to 2021). Sudden impairment of blood flow to a part of the brain due to occlusion or rupture of an artery to the brain. "In addition, netrin-1 and its receptors DCC and Unc5B have been demonstrated to be involved in the exercise-induced functional recovery of rats after stroke." (PMID 29017609, 2017).
agenesis of the corpus callosum (1 paper, 2025). "Recent research has confirmed an intrinsic connection between congenital agenesis of the corpus callosum (ACC) and MRMV1, which is associated with mutations in the deleted in colorectal carcinoma (DCC) gene." (PMID 41239616, 2025).